CTLA4 (cytotoxic T-lymphocyte associated protein 4)
Diseases named in the same sentence as CTLA4 in open-access papers (continued):
Sharing a sentence is not in itself a finding about the gene and the disease.
breast carcinoma (continued). "In this study, we set out to evaluate the syngeneic NF9006 breast cancer mouse model with the aim to use it for the investigation of anti-CTLA-4-based immunotherapy after low-dose irradiation delivered by application of [177Lu]Lu-DOTA-folate." (PMID 33078260, 2021). "The most pronounced influence of MCF-7 breast cancer cells on lymphocytes was found when analyzing CD4+CTLA-4+/PD-1+ and CD8+CTLA-4+/PD-1+ frequencies in total lymphocytes." (PMID 34440813, 2021). "Recent studies on breast cancer demonstrated the significance of inhibitory anti-CTLA-4 and anti-PD-1 in the regulation of disease progression." (PMID 34440813, 2021). "The first inhibitory immune checkpoint receptor studied in the clinic, CTLA-4, was previously shown to be present as a surface molecule on solid tumor cell lines including breast carcinomas and osteosarcomas." (PMID 33823818, 2021). "Originally approved for the treatment of metastatic melanoma, anti-CTLA-4 is now being tested for treating breast cancer in clinical trials combined with other immunostimulatory agents." (PMID 33411055, 2021). "The triple-negative model of breast cancer was the one responding with growth inhibition to additional implementation with anti-CTLA-4." (PMID 34440813, 2021). "Anti-CTLA4 was tested in combination with single-dose and fractionated radiotherapy in a mouse breast cancer model to determine if it can produce what is known as an “abscopal effect” on secondary and primary tumors." (PMID 34729098, 2021). "There have currently been some clinical trials assessing the immunity and effectiveness of CTLA-4 block in the breast cancer." (PMID 33724757, 2021). "While CTLA-4 is a protein related to the inflammatory response that is increased in breast cancer patients, contributing to immune downregulation, TNF-α is a pro-inflammatory cytokine that induces apoptosis promoted by the absence of leptin." (PMID 33644151, 2021). "This combination was investigated in preclinical settings in breast cancer and metronomic cyclophosphamide was shown to enhance the outcome of anti-CTLA4 therapy." (PMID 34729098, 2021). "Inhibiting the RANKL/RANK signaling pathway can transform the immune environment and enhance the efficacy of anti-CTLA-4 and anti-PD-1 treatment on breast cancer." (PMID 34877360, 2021). "Although CTLA-4 block is an attractive approach for treating the breast cancer, its immunity-related toxicity is still a matter of concern." (PMID 33724757, 2021). "The study shows that radiotherapy, PLGA-R837@Cat and anti-CTLA-4 Ab, allowed for the best results also in the breast cancer orthotopic model (4T1), with superior efficacy with respect to PLGA-R837@Cat+X-ray, surgery+anti-CTLA-4 and surgery+PLGA-R837@Cat." (PMID 33800368, 2021). "For example, LY3022855, a CSF1R blocker used as a single agent or in combination with Durvalumab (anti-PDL1 mAb) or Tremelimumab (anti-CTLA4 mAb) for patients with a solid tumors, including breast cancers." (PMID 33747948, 2021). "The effect of tremelimumab (anti-CTLA-4 antibody) in combination with exemestane - a steroidal aromatase inhibitor - was evaluated in breast cancer." (PMID 34729098, 2021). "In the past few decades, most of studies have been focused on the role of PD-1/PDL-1, and CTLA-4 in breast cancer." (PMID 33721026, 2021). "Breast cancer cells were co-cultured with lymphocytes to evaluate the effects of CTLA-4 and PD-1 inhibition." (PMID 34440813, 2021). "Examples of immune targets under investigation for the treatment of specific breast cancer subtypes include B7-H3, LAG3 and CTLA4; there is also interest in assessing the role of Bcl-2 inhibition in selected patients with breast cancer." (PMID 34838031, 2021). "Only a few studies investigated the effects of CTLA4 blockade on breast cancer, most of which combined CTLA4 blocking drugs with other treatments such as aromatase inhibitors, radiotherapy, and chemotherapy." (PMID 34729098, 2021).
breast carcinoma (continued). "The immunity of another anti-CTLA-4 mAb, tremelimumab, was evaluated as a single treatment or with anti-PD-L1 (durvalumab) in advanced breast cancer treatment (NCT02527434 and NCT01975831)." (PMID 33724757, 2021). "The obtained results indicate the advantageous properties of CTLA-4 blockage within lymphocytes in the suppression of breast cancer cell proliferation." (PMID 34440813, 2021). "Recently, several groups have observed that the combination of anti-CTLA-4 check point inhibition with SWCNT enhanced PTT has the potential to promote a robust immune response in breast cancer." (PMID 33411055, 2021). "Cytotoxic T lymphocyte antigen 4 (CTLA4) and programmed cell death protein 1 (PD-1)/programmed cell death protein-ligand 1 (PD-L1) are critical immune checkpoints for breast cancer." (PMID 34631507, 2021). "The limited success of immune checkpoints, like CTLA-4 or PD-1, in clinical trials for breast cancer patients, has prompted research to find alternative targets." (PMID 33747948, 2021). "The number of studies focusing on the assessment of CTLA-4/ PD-1 inhibition on interactions between lymphocytes and different subtypes of breast cancer remains scarce." (PMID 34440813, 2021). "Another research group showed that the supportive potential of CTLA-4 blockage in HER2/Neu antibody and triciribine combination treatment of mouse mammary tumors was associated with increased concentrations of IFN-gamma in tumor lysates and plasma." (PMID 34440813, 2021). "Further studies will be done in other breast cancer cell lines and cardiomyocytes (i.e., primary ventricular cardiomyocytes) exposed to CTLA-4 blocking agents as well as other immune check point inhibitors (PD-1 or PDL-1 blocking agents)." (PMID 33096896, 2020). "Accordingly, our findings revealed an association between cats with mammary carcinoma and higher serum levels of two pro-inflammatory cytokines (TNF-α and IL-6), positively correlated with serum CTLA-4 levels, as reported in humans and mice." (PMID 32123292, 2020). "Lastly, we found that NRP1, NRP2, PLXNA1, C1, and D1 had the highest correlation with the expression of immune checkpoint molecules PD1/PDL1 and CTLA-4 in breast cancer." (PMID 32640719, 2020). "Firstly, we investigated the intracellular and surface expression of CTLA-4 in breast cancer cell lines by Fluorescence-activated cell sorting (FACS) analysis." (PMID 33096896, 2020). "Intriguingly, a positive correlation of mRNA expression was observed between eight immune-related genes and PD-L1, PD-1, and CTLA4 in patients with breast cancer." (PMID 33042828, 2020). "Serum CTLA-4 levels were detected in 23 of the 54 cats with mammary carcinoma (43%), showing a median of 459.4 pg/mL (range 77–999.3 pg/mL), contrasting with undetectable levels in all healthy animals (detection limit = 31.3 pg/mL)." (PMID 32123292, 2020). "ICON is to our knowledge the first clinical trial combining chemotherapy with PD-1 and CTLA-4 blockade in breast cancer." (PMID 32620163, 2020). "As expected and reported in the literature, CTLA-4 expression in the breast cancer cell lines was detectable; the higher expression was seen in MDA-MB-231 cells compared to MCF-7." (PMID 33096896, 2020). "Based on reports of all types of breast cancer, CTLA-4 is an independent predictor of shorter DFS and OS in breast cancer." (PMID 33033520, 2020). "A strong positive correlation was found in cats with HER2-positive mammary carcinomas between the serum PD-1 levels and serum PD-L1 (r = 0.923), CTLA-4 (r = 0.975) and TNF-α (r = 0.968) levels." (PMID 32481540, 2020). "An increase in peripheral ICOS+CD4+ T cells has been also shown as a good clinical ICB responses in patients with hormone-responsive advanced breast cancer, which were treated with the anti-CTLA4 tremelimumab in combination with exemestane." (PMID 32258038, 2020). "In breast cancer, animal studies have demonstrated a substantial advantage by adding anti-CTLA-4 to anti-PD-1 and chemotherapy." (PMID 32620163, 2020).
breast carcinoma (continued). "Accordingly, serum CTLA-4 levels are increased in cats with mammary carcinoma, as well as in human malignant tumors." (PMID 32481540, 2020). "In this study, we analyzed the expression of CTLA-4 in different types of breast cancer, and then selected TNBC to comprehensively analyze the expression of CTLA related genes." (PMID 33033520, 2020). "We demonstrated that CTLA-4 expressed on breast cancer cells, mainly in the membrane of HCC1937 cell line, is functional and induces the activation of the MAP kinase pathway, while AKT signaling is abrogated." (PMID 32850353, 2020). "More recently, CTLA-4 has been reported to be over-expressed in a high proportion of breast cancer samples." (PMID 32850353, 2020). "Serum CTLA-4 levels were also significantly increased in cats with mammary carcinomas immunohistochemically classified as HER-2-positive (P < 0.001)." (PMID 32123292, 2020). "Anti-CTLA4 antibody tremelimumab in combination with exemestane supported tumor immunosuppression in ER+ breast cancer patients (phase I)." (PMID 32947901, 2020). "Previous analyses have concluded that TNBC, as the type of breast cancer with the worst prognosis, has significantly higher expression of CTLA-4 than other molecular types of breast cancer." (PMID 33033520, 2020). "A cogent demonstration of this immune suppression was demonstrated in breast cancer cells, which have been shown to express CTLA-4." (PMID 33384695, 2020). "Strikingly, the only early breast cancer patient who died was concomitantly treated for a systemic disease by a CTLA-4 signaling modulator, suggesting that breast cancer per se is not a major contributor to COVID-19 mortality." (PMID 32460829, 2020). "Ixabepilone is an FDA-approved small-molecule drug for the treatment of metastatic or locally advanced breast cancer, and the drug was found to exert a synergistic effect with the blocking effect of CTLA-4." (PMID 32190660, 2020). "Immune checkpoint inhibitors such as anti-PD-1/PD-L1 and CTLA-4 antibodies have added another therapeutic approach, immunotherapy, to fight breast cancer." (PMID 33457427, 2020). "We believe that a comprehensive analysis of CTLA-4 in breast cancer is necessary in order to explore its potential for use alone or in combination with other therapies." (PMID 33033520, 2020). "For doing this, the Wilcoxon test was applied to calculate the difference between the two breast cancer clusters in the expression levels of PD-1, PD-L1 and CTLA4." (PMID 32179831, 2020). "Overexpression of CTLA4 can increase numbers of Treg cells and thereby influence breast cancer pathogenesis and development." (PMID 32756008, 2020). "In this study, CTLA-4+ breast cancer cells suppressed dendritic cell maturation, antigen presentation, and inflammatory cytokine expression, ultimately dampening TH1 and CTL responses." (PMID 33384695, 2020). "Collectively, we found that breast cancer cells upregulated the expression of PD-1, CTLA-4, TIM-3 and LAG-3 in the different subsets of CD4+ T cells." (PMID 31614877, 2019). "In the breast cancer model, treatment with anti-CTLA-4 given IP and intra-tumor (IT) SS1P injected into one of two tumors growing in the same mouse resulted in complete regressions in 86% of the injected tumors and 53% of non-injected tumors." (PMID 30621280, 2019). "In a study on a mouse model of breast cancer in which a combination of CTLA-4 blockade and RT was used, the antibody was administered at different time points with the best abscopal response being seen when the first dose of antibody was given during RT." (PMID 31182960, 2019). "In another study using ipilimumab (anti-CTLA4) in early stage breast cancer, the researchers observed that at a dose of 10 mg/kg, ipilimumab was tolerated and led to increase in antitumor Th1 response as well as ICOS levels." (PMID 31366131, 2019).
breast carcinoma (continued). "The addition of anti-CTLA-4 monoclonal antibody was able to reverse dendritic cell suppression and activate CD8+ T cells and induce apoptosis of CTLA-4+ breast cancer cells." (PMID 31430935, 2019). "We evaluated the combination of locally delivered anti-mesothelin immunotoxins and systemic anti-CTLA-4 in both the 66C14-M murine breast cancer model and the AE17-M murine mesothelioma model." (PMID 30621280, 2019). "In breast cancer, anti-CTLA-4 treatment was used for the first time in a Phase I trial to treat patients with advanced ER+ breast cancer." (PMID 31366131, 2019). "Together, cryoablation before mastectomy is feasible and its combination with immunotherapy, consisting of NK cell therapy, DC-CIK or anti-CTLA-4 antibody, is safe and effective in different stages in breast cancer." (PMID 31111237, 2019). "In preclinical breast cancer models, an abscopal effect was induced only by fractionated radiation, not single-dose radiation, when given in combination with anti-CTLA4." (PMID 29556198, 2018). "In primary breast cancers there is an increased expression of CTLA-4, compared with normal breast tissue." (PMID 29390966, 2018). "Currently, there are no clinical trials on DcR3 however, there are several ongoing in breast cancer for blockading CTLA4, TGF-β, PD-1/PD-L1, CLTA4 and PD-1, and chimeric antigen receptor T-cell therapy (CAR-T)." (PMID 30513096, 2018). "The results of this study have found a significant expression of CTLA-4 (>50%), in a systematic manner, in breast cancers." (PMID 29672601, 2018). "LY6E promotes signaling via the TGF-β pathway leading to increased drug resistance, PDL1 and CTLA4 expression, and immune escape in breast cancer." (PMID 29545934, 2018). "Immunotherapies to restore T-cell responses, such as PD-1, PD-L1, and CTLA-4, are emerging as anti-tumor therapies for various cancer types, including breast cancer." (PMID 29912871, 2018). "There were, however, significantly higher levels of tumour-infiltrating FOXP3+ and CTLA-4+ T cells in ALN metastases compared with the levels in the corresponding primary breast cancers (p = 0.026, p = 0.036, respectively)." (PMID 29390966, 2018). "At the outset, CTLA-4 is overexpressed in more than 50% of breast carcinomas, while PD-L1 is expressed in less than 4% of breast carcinomas, based on the review of the randomly assembled TMA samples." (PMID 29672601, 2018). "The significant point to note in this juxtaposition, is that CTLA-4 is shown to be a more important immune checkpoint marker than PD-L1 in breast cancers as its potential use in immunotherapy." (PMID 29672601, 2018). "When RT was combined with dual checkpoint blockade (anti-PD-L1 plus anti-CTLA-4), further improvements in complete responses (CRs) and survival were achieved in a preclinical model of breast cancer (RT plus anti-CTLA-4 resistant cell line)." (PMID 30360504, 2018). "The presence of CTLA-4 and PD-L1 (small subset) as detected by IHC have the potential to be used not only as a prognostic marker in the breast cancers, but as a potential predictive marker for the immunotherapeutic responses." (PMID 29672601, 2018). "Immune-mediated inhibition of metastases after treatment with local radiation and CTLA-4 blockade in a mouse model of breast cancer." (PMID 30400835, 2018). "In fact, the rate of the PD-L1 positivity is very low in the overall breast cancers based on the findings in the current study, whereas CTLA-4 has a much higher rate of over-expression." (PMID 29672601, 2018). "In our study, we have shown that lower grade breast carcinomas, which tend to have better prognoses, had a higher rate of CTLA-4 expression than high grade carcinomas." (PMID 29672601, 2018). "There is, however, a dearth of publications regarding CTLA-4+ T cells and breast cancer, either in the primary tumour or ALNs." (PMID 29390966, 2018).
breast carcinoma (continued). "Summary of all breast carcinoma cores with the CTLA-4 reactions and their scores based on the “Interpretations” in which 1+ intensities, with the scores of “1a” and “2a”, were considered as “Negative”." (PMID 29672601, 2018). "Summary and the statistical analyses of the breast tissue cores with the rate of CTLA-4 positivity in different groups of the breast carcinomas." (PMID 29672601, 2018). "In this study, we demonstrated for the first time that CTLA-4 expressed on breast cancer cells was functional and CTLA-4+BCCs played an inhibitory role on the maturation and function of DCs, which was CTLA-4-dependent." (PMID 28099147, 2017). "A positive impact of CTLA-4 on outcome has also been reported for the expression in breast cancer related interstitial lymphocytes." (PMID 28707078, 2017). "HDACi significantly enhanced the in vivo response to PD-1/CTLA-4 blockade in the triple-negative 4T1 breast cancer mouse model, the only currently available experimental system with functional resemblance to human TNBC." (PMID 29371976, 2017). "Higher clinical stage and promoted axillary lymph node metastasis can be found in breast cancer patients with higher CTLA-4 mRNA levels." (PMID 28211499, 2017). "The direct effects of CTLA-4 antibody on the biological behavior of breast cancer cells were also investigated." (PMID 28099147, 2017). "Some SNPs in six immunological genes, BTLA, ITGAL, CTLA4, ICOS, PDCD1, and VTCN1 were reported as breast cancer risk mutations in previous studies." (PMID 27911271, 2017). "In this study, we first investigated intracellular and surface expression of CTLA-4 in 4 breast cancer cell lines by FACS analysis." (PMID 28099147, 2017). "This study showed that LPS-stimulated human dendritic cells (DCs) decreased the expression of HLA-DR, CD83 and costimulatory molecules (CD40, CD80 and CD86) following coculturing with CTLA-4+ breast cancer cells." (PMID 28099147, 2017). "Our observations are in line with a previous report showing decreased lung metastases after RT and CTLA‐4 blockade in a mouse model of breast cancer." (PMID 27932443, 2017). "Breast cancer patients with higher CTLA-4 mRNA levels had obvious axillary lymph node metastases and a higher clinical stage." (PMID 26918337, 2016). "In solid tumors, cytoplasmic and surface CTLA-4 expression was detected in all six osteosarcoma specimens and in all five cases of ductal breast carcinomas examined." (PMID 26918337, 2016). "There was also a significant reduction of CTLA-4+ T cells in the blood (% [p = 0.017], AbNs [p = 0.001]) and breast cancers (stromal [p = 0.029]) following 8 cycles of NAC in the same cohort of 16 patients." (PMID 27777963, 2016). "In human medicine, peripheral lymphocytes of patients with some cancers, including lung cancer, breast cancer, and leukemia, exhibit increased expression of the CTLA-4 protein or gene." (PMID 26901565, 2016). "CTLA-4 expressed in cytoplasm of breast cancer cells and in cytoplasm and cell membranes of interstitial lymphocytes." (PMID 25893809, 2015). "Plasma soluble CTLA-4 and CTLA-4 expression in peripheral mononuclear cells of breast cancer patients were higher than in normal controls." (PMID 25893809, 2015). "CTLA-4 expression varied greatly among breast cancer patients; we identified CTLA-4 expression profiles in terms of CTLA-4 expression in lymphocytes and tumor cells." (PMID 25893809, 2015). "We found CTLA-4 expression in primary breast cancer lesions to have potential prognostic value; higher CTLA-4 expression in breast cancer cells was associated with worse prognosis, and higher density of interstitial CTLA-4+ lymphocytes with better prognosis." (PMID 25893809, 2015). "Nonetheless, the relationship between prognosis and CTLA-4 expression in breast cancer remains elusive." (PMID 25893809, 2015). "Breast cancer cells reportedly also expressed CTLA-4, which was principally found in cytoplasm of cancer cells." (PMID 25893809, 2015).